METTL3 (methyltransferase 3, N6-adenosine-methyltransferase complex catalytic subunit)
Diseases named in the same sentence as METTL3 in open-access papers (continued):
Sharing a sentence is not in itself a finding about the gene and the disease.
glioblastoma (continued). "The large amount of data collected and analyzed in this paper holds a great interest for the comprehension of METTL3-mediated m6A methylation in glioblastoma, even if a limitation of this study is that almost all analyses are in silico ones, based on a single GSC line." (PMID 32316617, 2020). "In glioblastoma, up-regulated METTL3 promotes GSCs maintenance and glioblastoma progression." (PMID 31801551, 2019). "Glioblastoma tumors exhibited elevated levels of METTL3 transcripts, and silencing METTL3 inhibited tumor growth coupled with prolonged survival of mice in vivo, suggesting the oncogenic role of METTL3 in glioblastoma." (PMID 31921660, 2019). "However, in another study on the function of m6A in glioblastoma, METTL3 overexpression inhibited stem cell growth and self-renewal, accompanied by suppressed tumor progression." (PMID 31921660, 2019). "Research on glioblastoma (GBM) has revealed that METTL3 enhances the stability of BUD13 mRNA through m6A methylation." (PMID 39295872, 2024). "However, the effect of METTL3 on VM in glioblastomas (GBM) appears to be different." (PMID 39098905, 2024). "For example, Li and his colleagues examined METTL3 mRNA in cancerous and paracancerous tissues from 36 clinical patients with glioblastoma (GBM) and found that METTL3 was highly expressed in GBM tissues compared with normal brain tissues." (PMID 35688823, 2022). "For example, in glioblastoma multiforme (GBM), METTL3 suppresses the proliferation and self-renewal of glioblastoma stem cells by enhancing m6A modification of ADAM19 and decreasing its expression, which suppressed the progression of GMB." (PMID 35281815, 2022). "By decreasing m6A levels of ADAM19 and increasing its expression in glioblastoma stem cells (GSCs), downregulation of METTL3/14 stimulates the proliferation and self-renewal of GSCs, ultimately resulting in GBM." (PMID 35159736, 2022). "In treating glioblastoma multiforme (GBM) with temozolomide, METTL3 increased the m6A modification of histone modify-related gene transcripts leading to the development of chemoresistance." (PMID 36517820, 2022). "Furthermore, METTL3 is a potential target in temozolomide-resistant glioblastoma." (PMID 36012529, 2022). "In glioblastoma (GBM), silencing METTL3 or overexpressing dominant-negative mutant METTL3 has been shown to suppress the growth and self-renewal of glioma stem cells (GSCs)." (PMID 34315512, 2021). "Radiation in GBM (glioblastoma) cells enhances the METTL3 expression and it increases the stability of SOX2 by recruiting hUR (human antigen R) and induces resistance against radiation." (PMID 33718113, 2020). "It has been reported that METTL3 enhances the translation of oncogenes such as epidermal growth factor receptor (EGFR), which is a key oncogene frequently amplified in glioblastomas." (PMID 41321637, 2025). "In glioblastoma, upregulated METTL3 methylates ADAR1 mRNA, increasing the resulting protein levels and establishing a protumor mechanism that involves METTL3, YTHDF1, and ADAR1." (PMID 39802639, 2025). "In glioblastoma and hepatocarcinoma, the expression level of SLC7A11 can be upregulated in an m6A-dependent manner with the assistance of METTL3 and IGF2BP1 via the inhibition of SLC7A11 mRNA degradation and increased SLC7A11 mRNA splicing and maturation." (PMID 41373022, 2025). "In glioblastoma, the study observed that SENP1-mediated deSUMOylation of methyltransferase like 3 (METTL3) promoted MYC protein expression, thereby accelerating self-renewal of tumor cells." (PMID 38389923, 2024). "We find modulation of METTL3 expression in our GIC/iNSC setting, and it is therefore conceivable that a similar mechanism contributes to mediating METTL7B’s impact on glioblastoma growth and invasion." (PMID 38848215, 2024). "It has also been shown that the self-renewal of glioblastoma stem cells (GSC) is regulated by m6A mRNA modification, and METTL3 downregulation significantly promotes tumor progression." (PMID 38166703, 2024).
glioblastoma (continued). "In glioblastoma, the overexpression of m6A methyltransferase METTL3 or METTL14, or correspondingly, the knockdown of FTO inhibited the growth and self-renewal of glioblastoma stem cells." (PMID 39198433, 2024). "In 2019, a new study validated earlier discoveries by demonstrating elevated METTL3 and YTHDF2 levels in samples from glioblastoma patients as compared with normal brain tissues." (PMID 38398118, 2024). "In glioblastoma, inhibition of METTL3 and METTL14 expression promotes the development of glioblastoma, and up-regulation of METTL3 or inhibition of FTO expression through MA2 delays tumor growth." (PMID 39033180, 2024). "The downregulation of METTL3 in glioblastoma cells (GBM) decreased the m6A modification levels of serine- and arginine-rich splicing factors (SRSF), which led to the YTHDC1-dependent nonsense-mediated decay (NMD) of SRSF transcripts and decreased SRSF protein expression." (PMID 36835633, 2023). "In glioblastoma, EGR1 contributes to the high expression of METTL3 by binding straightly to the promoter of METTL3." (PMID 37996892, 2023). "In support of this phenomenon, METTL3 or METTL14 downregulation has markedly promoted the proliferation, self-renewal, growth, and tumorigenesis of human glioblastoma stem cells (GSCs)." (PMID 38072944, 2023). "In glioblastoma, ADAR1 elevates CDK2 expression by binding to CDK2, while METTL3 upregulates ADAR1 protein expression and promotes G1/S phase transition." (PMID 37996892, 2023). "Specifically, silencing METTL3 enhanced the sensitivity of (glioblastoma stem cells) GSCs to γ-H2AX and efficient DNA repair, resulting in rescuing glioblastomas’ radiosensitivity." (PMID 36517820, 2022). "Meanwhile, another group of researchers found that METTL3 upregulation was observed to predict poorer patient survival and increased SOX2 mRNA expression and stability, promoting the growth of glioblastoma stem cells and shortening the survival time of mice." (PMID 36360287, 2022). "In GBM, overexpressing METTL3 reduces CD44 expression and sphere-formation rate of glioblastoma stem cells (GSCs), indicating that it suppresses GSC growth and self-renewal, whose presence confers cell resistance to radiotherapy and chemotherapy." (PMID 35864970, 2022). "At the same time, the knockdown of METTL3 and METTL14 dramatically promotes human glioblastoma stem cell growth, self-renewal, and tumorigenesis." (PMID 36012529, 2022). "METTL3 and METTL14 are essential m6A methyltransferases and have been reported to be involved in tumorigenesis of glioblastoma stem cells." (PMID 34863175, 2021). "Our data reveal the existence of a new pro-tumoral pathway in glioblastoma (METTL3/ADAR1) and indicate ADAR1 as one of the main targets of METTL3 controlling cell proliferation and tumor growth." (PMID 33509238, 2021). "For example, abundant METTL3 expression in AML, liver cancer and glioblastoma promotes the occurrence and development of tumours." (PMID 33932138, 2021). "Downregulation of METTL3 or METTL14 can promote proliferation and self-renewal of glioblastoma stem cells by reducing the m6A level on ADAM19 mRNA, which enhances its stability and finally promotes the occurrence of glioblastoma." (PMID 34900689, 2021). "We report that the ADAR1 protein level is increased by METTL3 and YTHDF1 proteins, both abundantly expressed in glioblastoma (GBM)." (PMID 33509238, 2021). "We further validated the regulation role of METTL3 in DLL3, NOTCH3, and HES1 and identify its influence in cell proliferation of glioblastoma cell lines via cell experiments." (PMID 34589481, 2021). "Despite the unanimously oncogenic functions of METTL3 and METTL14 in all these cancer types, in glioblastoma and HCC several reports have demonstrated both, oncogenic and tumour suppressive roles." (PMID 33461542, 2021).
glioblastoma (continued). "Here, we show that METTL3, upregulated in glioblastoma, methylates ADAR1 mRNA and increases its protein level leading to a pro-tumorigenic mechanism connecting METTL3, YTHDF1, and ADAR1." (PMID 33509238, 2021). "In this study, METTL3 was found to increase the stability and expression of SOX2 mRNA, promoted the growth of glioblastoma stem cells (GSCs), and prolonged survival in mice." (PMID 33461542, 2021). "Nevertheless, the oncogenic role of METTL3 was shown in another study, where METTL3-mediated m6A modification enhanced SOX2 mRNA stability, METTL3 knockdown decreased glioblastoma stem cell growth in a SOX2-dependent manner." (PMID 32709063, 2020). "METTL3 and METTL14 knockdown was observed to upregulate the expression of several oncogenes such as ADAM19, EPHA3 and KLF4 in glioblastoma stem cells (GBCs)." (PMID 32194861, 2020). "Mechanistically, by combining m6A-seq analysis in GSCs, and RNA-seq in GSCs depleted of METTL3 or METTL14, the authors revealed key mediators of the functional effects of m6A RNA methylation perturbation in glioblastoma initiating cells." (PMID 32316617, 2020). "With respect to m6A writers, one study showed that knockdown of METTL3 or METTL14 facilitates stemness and tumorigenesis of glioblastoma stem cells." (PMID 32850334, 2020). "In glioblastoma tumor, the key m6A writers known to have a potential role in tumor course are METTL14 and METTL3, for which the experimental knocking-down expression in cellular models results in tumor cell growth." (PMID 30654440, 2019). "Furthermore, the authors investigated the impact of BCL-X splicing alteration on METTL3-silencing phenotypes by combined knockdown of METTL3 and BCL-XS in glioblastoma cells." (PMID 38398118, 2024). "A micropeptide named AF127577.4-ORF, encoded by its namesake lncRNA, has been shown to diminish glioblastoma cell proliferation through its regulation of METTL3 and the ERK pathway, which could be a promising approach to glioblastoma management." (PMID 39311199, 2024). "For human glioblastoma U251 cells and human colon cancer HCT116 cells, the results strongly supported that the m6A writers METTL3 and METTL14 were down‐regulated upon the addition of bile acids, especially at high concentrations." (PMID 38713722, 2024). "In contrast, METTL3 and METTL14 showed a tumor-suppressive role in glioblastoma stem cells." (PMID 38503745, 2024). "YY1 transcriptionally upregulates sentrin/SUMO-specific protease 1 (SENP1) and enhances the methylase activity of methyltransferase-like 3 (METTL3), leading to increased N6-Methyladenosine (m6A)-modification levels in MYC mRNA, which promotes the self-renewal of glioblastoma stem cells (GSCs)." (PMID 37444616, 2023). "In glioblastoma CSCs, YY1 mediates self-renewal through regulation of the SENP1/METTL3/MYC axis." (PMID 37444616, 2023). "Dysregulation of METTL3 and METTL14 has been found in liver cancer, lung cancer and glioblastoma." (PMID 36077054, 2022). "The effect of METTL3 inhibitors has not been reported on glioblastoma, but we believe that it is worthy of future study." (PMID 35625706, 2022). "In order to investigate whether ADAR1 per se promotes cell proliferation in glioblastoma independently of METTL3, we silenced ADAR1 in several glioblastoma cell lines (U87MG, U118MG, A172, and T98G) and we tested cell proliferation over time." (PMID 33509238, 2021). "METTL3 plays an oncogenic role by modulating nonsense-mediated mRNA decay (NMD) of splicing factors and alternative splicing of BCLX and NCOR2 isoform switches in glioblastoma." (PMID 33718165, 2021).
glioblastoma (continued). "Paradoxically, the m6A methyltransferase METTL3 was reported to have dual roles in cancer, acting as an oncogene in AML, breast, and liver cancers, and as a tumor suppressor in glioblastoma and endometrial cancers." (PMID 34631715, 2021). "METTL3 maintains the stability of a specific set of transcripts, such as apoptosis pathways and glial differentiation genes including SRSF1/2/3/6/11, CASP3/7, CASPB, DFFB, BMP2, LIF, IL1B, and HES1 in glioblastoma." (PMID 33718165, 2021). "They further showed that knockdown of METTL3 decreases m6A modification of the splicing factor SRSF, leading to YTHDC1-dependent nonsense-mediated mRNA decay of the SRSF transcripts and alternative splicing isoform switches in glioblastoma." (PMID 32854717, 2020). "For instance, the increased expression of METTL3 and METTL14 in brain and CNS cancer might explain their promotion role in growth and tumorigenesis of glioblastoma stem cells." (PMID 30953473, 2019). "Regardless of its tumour suppressor role in glioblastoma, certain studies depict that METTL3 promotes cell growth, survival and invasion in several cancers." (PMID 30039919, 2018). "Individual m6A RNA methylation regulators, including METTL3, ALKBH5, YTHDF2, and IGF2BP3, have been assessed in patient datasets to examine their expression levels across normal tissues, lower-grade gliomas, and glioblastomas, as well as their prognostic significance." (PMID 38398118, 2024). "According to large-scale glioblastoma genomics and clinical data from the Chinese Glioma Genome Atlas (CGGA) and The Cancer Genome Atlas (TCGA), the main regulatory factor of m6A methylation, METTL3, shows differential expression in glioblastomas and is closely associated with disease progression." (PMID 39473440, 2024). "However, METTL3 and ALKBH5 were both found to maintain the growth of glioblastoma cells." (PMID 38398118, 2024). "In glioblastoma, we observed that both METTL3 and METTL14 are highly expressed compared to normal brain; additionally, we found that the A-to-I overall editing is decreased in GBM, despite the high levels of ADAR1 protein found in this type of tumor." (PMID 33509238, 2021). "Conversely, some m6A genes have been found to act as tumor suppressor genes or oncogenes, for example, METTL3 and METTL14, in neurological tumors such as glioblastoma (GBM)." (PMID 33519919, 2020). "This study revealed the biological significance of m6A modification in glioblastoma biology, defining the role of m6A modification in GSC self-renewal and tumorigenesis by targeting multiple components of the m6A regulatory machinery, including METTL3, METTL14, and FTO." (PMID 28297667, 2017). "However, another study revealed an opposing effect of mitophagy on cancer cells, as the platelet-derived growth factor (PDGF)-METTL3 axis could downregulate the expression of optineurin (OPTN), inhibiting mitophagy and promoting cancer stem cell maintenance in glioblastoma." (PMID 41373022, 2025). "However, METTL3 can also inhibit ferroptosis by downregulating SLC7A11 in lung cancer and glioblastoma (GBM)." (PMID 40271153, 2025). "Similarly, in a glioblastoma (GBM) stem cells (GSCs) related work, platelet-derived growth factor (PDGF) ligand stimulate early growth response 1 (EGR1) transcription to induce METTL3 to promote GSC proliferation and self-renewal." (PMID 38562618, 2024). "In glioblastoma (GBM), METTL3 exerts an oncogenic effect through modulating nonsense-mediated mRNA decay of splicing factors and alternative splicing isoform switches." (PMID 31801551, 2019).
glioma (131 papers, 2016 to 2025). A benign or malignant brain and spinal cord tumor that arises from glial cells (astrocytes, oligodendrocytes, ependymal cells). "Associations between glioma malignancy grade and the expression of m6 A writers (METTL3, METTL14, WTAP, and RBM15), the reader YTHDF, and erasers (ALKBH5 and FTO) are shown." (PMID 40382536, 2025). "Collectively, these data suggested that METTL3-mediated m6A modification is associated with the upregulation of LINC01003 in glioma." (PMID 37270527, 2023). "Other studies corroborated the association between high METTL3 expression and reduced glioma proliferation; however, METTL3 silencing was shown to suppress vasculogenic mimicry, important for tumour angiogenesis." (PMID 36831575, 2023). "METTL3 is poorly expressed in glioma tissues, and METTL3 deficiency facilitates glioma cell proliferation." (PMID 35474040, 2022). "Our recent findings also demonstrate that METTL3 expression is significantly deceased in IDH-wildtype glioma, and METTL3 expression is positively associated with a higher malignant grade and poorer prognosis of IDH-wildtype gliomas but not IDH-mutant gliomas." (PMID 34246306, 2021). "Further, we conclude that successful execution of oncogenic pathways requires METTL3 and the associated m6A modification, thus implicating an oncogenic role for METTL3 through its direct and indirect targets in glioma." (PMID 30781903, 2019). "Notably, METTL3 overexpression is closely linked to glioma clinical stage, and its inhibition reduces m6A enrichment on splicing factor SRSF proteins, thereby decreasing their stability." (PMID 41390674, 2025). "METTL3-mediated m6A methylation is associated with treatment resistance in gliomas." (PMID 38474421, 2024). "METTL3 downregulation underlies a potential mechanism of glioma tumorigenesis." (PMID 35474040, 2022). "We found that METTL3 and the associated m6A modification are essential for glioma stem cell growth." (PMID 29460395, 2018). "Functionally, METTL3 overexpression promoted glioma cell proliferation, but this effect was significantly attenuated when EIF3J-AS1 expression was suppressed." (PMID 41390674, 2025). "Our findings revealed that miR-101 suppressed EIF3J-AS1 expression and function in glioma cells by reducing METTL3-mediated m6A modification of EIF3J-AS1." (PMID 41390674, 2025). "Similar ceRNA-driven mechanisms involving miR-376a-3p/YAP1 in glioma, miR-590-5p/METTL3 in lung adenocarcinoma, and miR-376a-3p/PRMT5 in prostate cancer further underscore its oncogenic potential." (PMID 40903777, 2025). "Conversely, the tumor-suppressive microRNA miR-101 inhibits EIF3J-AS1 expression by targeting METTL3, thereby inducing autophagy in glioma cells." (PMID 41390674, 2025). "METTL3 promotes the self-renewal of glioma stem cells by regulating LINC00839 to activate the Wnt/β-catenin signaling pathway, leading to radiotherapy resistance in GBM." (PMID 40823093, 2025). "Subsequently, we conducted colony formation and CCK8 assays to evaluate the oncogenic potential of METTL3 in glioma." (PMID 41321637, 2025). "In summary, METTL3-mediated m6A methylations represent crucial factors contributing to drug resistance in gliomas." (PMID 40469294, 2025). "Although many studies have reported that METTL3 promotes the occurrence and progression of gliomas, METTL3 also has inhibitory effects on glioma occurrence." (PMID 40469294, 2025). "Overall, we found that METTL3 is highly expressed in high-grade gliomas and plays a critical role in promoting glioma tumorigenesis." (PMID 41321637, 2025). "Our findings demonstrate that USP25 promotes glioma proliferation by stabilizing METTL3 in the cytoplasm, thereby enhancing EGFR translation." (PMID 41321637, 2025). "m6A-mediated RNA modifications influence glioma initiation and progression, with METTL3 upregulation promoting tumor progression via lncRNA modulation." (PMID 41390674, 2025).